ARHGAP5 (Rho GTPase activating protein 5)
Description:
GTPase-activating protein for Rho family members.
Synonyms: RHOGAP5; p190-B; p190BRhoGAP; GFI2
Tractability: Antibody: UniProt places it where antibodies can reach, with high confidence; its Gene Ontology location is reachable by antibodies, with medium confidence. PROTAC: ubiquitination databases record sites on it; its protein half-life has been measured.
Gene: Protein-coding gene on chromosome 14 (32,075,794 to 32,159,728, forward strand). Ensembl gene ENSG00000100852.
Subcellular location: Cytoplasm; Cell membrane
Subcellular location (Human Protein Atlas): Cytosol; Endoplasmic reticulum
Pathways (Reactome):
Signal Transduction: CDC42 GTPase cycle; RAC1 GTPase cycle; RAC3 GTPase cycle; RHOA GTPase cycle; RHOB GTPase cycle; RHOC GTPase cycle; RHOD GTPase cycle; RHOF GTPase cycle; RHOG GTPase cycle; RHOJ GTPase cycle; RHOQ GTPase cycle; RND1 GTPase cycle; RND2 GTPase cycle; RND3 GTPase cycle
Gene Ontology:
Molecular function: protein binding; SH2 domain binding; GTPase activator activity; GTPase activity
Biological process: cell adhesion; regulation of cell size; regulation of small GTPase mediated signal transduction; Rho protein signal transduction; mammary gland development; signal transduction
Cellular component: cytosol; plasma membrane; cytoplasm
Genetic constraint (gnomAD): Loss-of-function variants: 21 observed, 102.43 expected, observed/expected ratio (o/e) 0.21, 90% interval 0.14 to 0.29. The upper end of that interval is the gene's LOEUF score, 0.29, which puts it in group 1 of 6, group 1 being the genes least tolerant of losing a copy. Missense variants: 1,322 observed, 1,695.8 expected, observed/expected ratio (o/e) 0.78, 90% interval 0.74 to 0.82. Synonymous variants: 539 observed, 578.65 expected, observed/expected ratio (o/e) 0.93, 90% interval 0.87 to 1.
Homologues: Orthologues: chimpanzee ARHGAP5 (100% identical), macaque ARHGAP5 (99% identical), dog ARHGAP5 (98% identical), pig ARHGAP5 (98% identical), rabbit ARHGAP5 (98% identical), mouse Arhgap5 (97% identical), rat Arhgap5 (97% identical), guinea pig ARHGAP5 (97% identical), tropical clawed frog arhgap5 (79% identical), zebrafish arhgap5 (74% identical). Paralogues in human: TCERG1 (11% identical), TCERG1L (6% identical).
Diseases named in the same sentence as ARHGAP5 in open-access papers:
ARHGAP5 is named in the same sentence as 32 diseases in open-access papers, as found by Europe PMC text mining. Sharing a sentence is not in itself a finding about the gene and the disease. The quoted sentences say what the papers report.
breast cancer (11 papers, 2009 to 2024). A primary or metastatic malignant neoplasm involving the breast. "Third, we found using IHC that ARHGAP5 expression was increased in breast cancer tissues compared to normal adjacent tissues." (PMID 36077054, 2022). "Loss of ADAR1 inhibits breast cancer growth and decreases METTL3 and ARHGAP5 expression levels in vivo." (PMID 36077054, 2022). "We further confirmed that ARHGAP5 is a target of METTL3 in breast cancer and promotes the proliferation, invasion and migration of breast cancer cells." (PMID 36077054, 2022). "In this study, we investigated the direct relationship between ADAR1 and METTL3 and found that overexpression and knockdown of ADAR1 respectively increased and decreased the expression levels of METTL3 and ARHGAP5 protein in breast cancer." (PMID 36077054, 2022). "We further performed a ribosome immunoprecipitation assay using Flag antibody to detect ARHGAP5 mRNA ribosome occupancy mediated by its m6A modification in breast cancer cells transfected with Flag-tagged RPL22 (ribosomal protein L22) upon YTHDF1 silencing." (PMID 36077054, 2022). "We demonstrate that ADAR1 promotes the proliferation, migration and invasion of breast cancer cells through the METTL3/ARHGAP5/YTHDF1 axis and establish that METTL3 is one of the main targets of ADAR1 controlling biological functions." (PMID 36077054, 2022). "However, details about how METTL3 regulates YTHDF1-recognized ARHGAP5 to promote breast cancer progression need to be investigated in the future." (PMID 36077054, 2022). "Moreover, ADAR1 edits the nearby ORF stop codon of METTL3 mRNA, leading to its binding site changing to miR-532-5p and resulting in increased METTL3 protein, which further targets ARHGAP5 to promote breast cancer progression in a YTHDF1-dependent manner." (PMID 36077054, 2022). "To investigate the biological roles of ADAR1/METTL3/ARHGAP5 in breast cancer cells, we silenced ARHGAP5 and overexpressed ADAR1-p150 or METTL3 proteins in the cell lines, and then performed CCK-8, colony formation and transwell assays to detect cell proliferation, migration and invasion." (PMID 36077054, 2022). "Therefore, we silenced YTHDF1 in breast cancer cell lines to investigate whether YTHDF1 has effects on ARHGAP5 mRNA and protein levels." (PMID 36077054, 2022). "Additionally, loss of ADAR1 inhibits breast cancer growth and decreases METTL3 and ARHGAP5 in vivo." (PMID 36077054, 2022). "To determine whether ADAR1 overexpression enhances ARHGAP5 expression through METTL3, we knocked down METTL3 and overexpressed ADAR1-p150 protein and knocked down ADAR1 and overexpressed METTL3 in breast cancer cell lines to detect ARHGAP5 expression level by qRT-PCR." (PMID 36077054, 2022). "All above results indicate that YHTDF1 is a reader protein of ARHGAP5 m6A in breast cancer cell lines and that METTL3/YTHDF1 controls ARHGAP5 protein levels with the translation modulation mechanism as the post-transcriptional axis." (PMID 36077054, 2022). "In summary, our findings revealed the novel molecular pathway ADAR1/METTL3/ARHGAP5 connecting ADAR1, METTL3 and YTHDF1, which may indicate ADAR1 or METTL3 as prognostic and therapeutical targets for the treatment of breast cancer." (PMID 36077054, 2022). "When we knocked down YTHDF1 using siRNAs in breast cancer cell lines, ARHGAP5 protein level was significantly decreased, without affecting its mRNA level." (PMID 36077054, 2022). "However, some studies argue that SIRT1 suppresses cancer cell migration and invasion, such as, by targeting ARHGAP5 in gastric cancer, by inhibiting the TGF-β/Smad4/MMP-7 axis in breast cancer and by regulating autophagy in CRC." (PMID 31068761, 2019). "We show that both ADAR1 and METTL3 are upregulated in breast cancer samples, and ADAR1 positively correlates with METTL3; ADAR1 edits METTL3 mRNA and changes its binding site to miR532-5p, leading to increased METTL3 protein, which further targets ARHGAP5, recognized by YTHDF1." (PMID 36077054, 2022).
lung carcinoma (11 papers, 2015 to 2023). "ARHGAP5 has been identified as an oncogene in lung cancer, hepatocellular carcinoma (HCC) and gastric cancer 39-41, and a tumor suppressor gene in invasive epithelial ovarian cancer." (PMID 32483433, 2020). "In lung cancer, miR-486-5p was identified as a tumor-suppressor by down-regulating protumorigenic ARHGAP5 and insulin growth factor signaling, and its down-regulation was also validated in plasma samples." (PMID 28030794, 2017). "miR-486–5p is one of the most downregulated miRNAs in lung tumor tissues and contributes to lung cancer progression and metastasis through regulating Rho GTPase-activating protein 5 (ARHGAP5)." (PMID 25793394, 2015). "A study on the mechanism of miR-486-5p revealed that the down-regulation of miR-486-5p could inhibit cell migration and invasion in vitro, and metastasis in vivo, in lung cancer by targeting genes such as ARHGAP5." (PMID 32359364, 2020).
gastric cancer (9 papers, 2018 to 2023). A primary or metastatic malignant neoplasm involving the stomach. "It was also proved that ARHGAP5 could be a prognostic marker of gastric cancer and the expression level of it was associated with invasive and migrative ability of nasopharyngeal carcinoma cells." (PMID 32429941, 2020). "As previous described, ARHGAP5 could work as an oncogene to promote tumor proliferation and migration in hepatocellular carcinoma and gastric cancer." (PMID 34285193, 2021). "In gastric cancer, SIRT1 suppresses migration and invasion by downregulating ARHGAP5 through inhibiting c-Jun." (PMID 36476606, 2022).
nasopharyngeal carcinoma (8 papers, 2015 to 2023). A carcinoma arising from the nasopharyngeal epithelium. "When overexpressed in 5–8F nasopharyngeal cancer xenografts, hsa-miR-744 induces ARHGAP5 expression to promote tumor growth and metastasis." (PMID 36902315, 2023). "Conversely, miR-744 increased the risk of pancreatic cancer, prostate cancer and nasopharyngeal carcinoma by activating the Wnt/β-catenin pathway, AMPK signaling, and transcriptional regulation of ARHGAP5, respectively." (PMID 36922987, 2023).
bladder cancer (5 papers, 2021 to 2024). "Our teammates did a research and found that circUBE2K could mediate RhoA associated bladder cancer phenotype via regulation of miR-516b-5p/ARHGAP5 axis." (PMID 36840946, 2023). "ARHGAP5, ARHGAP17 and ARHGAP24 promoted bladder cancer progression by establishing a tumor-promoting microenvironment or cellular mechanical property-mediated cell motility." (PMID 37175461, 2023).
colorectal cancer (5 papers, 2020 to 2025). A primary or metastatic malignant neoplasm that affects the colon or rectum. "ARHGAP5 suppression leads to decreased wound healing, migration, and invasion in DLD1 and SW480 colorectal cancer cells." (PMID 35853889, 2022). "ARHGAP5 drives colorectal cancer metastasis through the negative regulation of RhoA activity." (PMID 38783033, 2024).
hepatocellular carcinoma (5 papers, 2016 to 2024). A malignant tumor that arises from hepatocytes. "In hepatocellular carcinoma, ARHGAP5 enhances cell spreading and migration by negatively modulating RhoA28." (PMID 38783033, 2024).
prostate carcinoma (4 papers, 2022 to 2024). A carcinoma that arises from epithelial cells of the prostate gland. "Similarly, hsa_circ_0003258 upregulates Rho GTPase activating protein 5 (ARHGAP5) via molecular sponge action to promote prostate cancer metastasis." (PMID 39090090, 2024).
cervical cancer (3 papers, 2017 to 2025). A primary or metastatic malignant neoplasm involving the cervix. "Several of these proteins are implicated in cervical cancer, including Ptgs2 (up), Hmox1 (up), Mkl1 (down), and Arhgap5 (down) (60, –, 63)." (PMID 41165329, 2025).
E. coli infection (2 papers, 2019 to 2024). "GSEA further confirmed significant enrichment in pathogenic Escherichia coli infection and sphingolipid metabolism in the ARHGAP5 high-expression group." (PMID 38783033, 2024).
lymph node metastasis (2 papers, 2015 to 2018). "Furthermore, when we included lymph node metastasis in overall survival analysis, the influence of ARHGAP5 remained significant." (PMID 30250020, 2018). "We found that the average expression level of ARHGAP5 was upregulated in late-stage NPC (P = 0.0192) in comparison with the early-stage NPC, and NPC with advanced lymph node metastasis (N2/N3 stage) had higher expression of ARHGAP5 (P = 0.0216)." (PMID 25961434, 2015). "High level of ARHGAP5 was positively correlated with that of miR-744 and with advanced stages of NPC, as well as with lymph node metastasis." (PMID 25961434, 2015).
non-small cell lung carcinoma (2 papers, 2015 to 2024). A group of at least three distinct histological types of lung cancer, including non-small cell squamous cell carcinoma, adenocarcinoma, and large cell carcinoma. "miR-486–5p may act as a tumor suppressor, contributing to the progression and metastasis of non-small cell lung cancer by targeting ARHGAP5." (PMID 25793394, 2015).
ovarian carcinoma (2 papers, 2019 to 2023). A malignant neoplasm originating from the surface ovarian epithelium. "The rs927062 variant of ARHGAP5 was found to be associated with increased endometrioid and invasive serious ovarian cancer risk and a statistically significant decrease of ARHGAP5 protein which would be predicted to increase Rac1 and RhoA activity." (PMID 31344967, 2019).
pancreatic cancer (2 papers, 2023 to 2024). "We also found a positive correlation between the expression levels of ARHGAP5 and its copy number variations, revealing a potential reason for the overexpression of ARHGAP5 in pancreatic cancer." (PMID 38783033, 2024). "Although the mechanism of action of ARHGAP5 and ARHGAP11A in pancreatic cancer is unclear, some oncogenic mechanisms have been identified in other tumors." (PMID 38783033, 2024). "Three potential prognostic markers (ARHGAP5, ARHGAP11A, and ARHGAP12) for pancreatic cancer were identified." (PMID 38783033, 2024). "However, a function for ARHGAP5 in pancreatic cancer has not been previously reported." (PMID 38783033, 2024).
colon cancer (1 paper, 2016). "Consistent with the findings of colon cancer tissue microarray, we also found that miR-126 significantly suppressed the expression of CXCR4, the activity of RhoA, and the expression of RhoGEF, ROCK, PI3K, PAK, PKN and up-regulated the expression of ARHGAP5 in colon cancer cells." (PMID 27517626, 2016).
cryptorchidism (1 paper, 2024). The failure of one or both testes of a male fetus to descend from the abdomen into the scrotum during the late part of pregnancy. "Causal P and LP variants were identified in 5 out of 13 patients with a history of cryptorchidism (three in FGFR1, one in ARHGAP5, and one in GNRH1), in 2 out of 8 patients with hearing impairment (CHD7 and FGFR1 genes), and in 2 out of 2 patients with renal agenesis (ANOS1 gene)." (PMID 39308770, 2024).
cyst (1 paper, 2020). A sac-like closed membranous structure that may be empty or contain fluid or amorphous material. "We conclude that a reduction in centrosomal PC1-ARHGAP35 interaction is likely to contribute to cyst formation in ADPKD but there could be compensation by other ARHGAPs such as ARHGAP5, -29, and others." (PMID 32663194, 2020).
gastric tumors (1 paper, 2022). "ARHGAP5 protein expression was significantly higher in primary gastric tumors as compared with adjacent non-tumor tissues by immunohistochemical (IHC) staining (P < 0.05)." (PMID 36307394, 2022).
osteoporosis (1 paper, 2022). A condition of reduced bone mass, with decreased cortical thickness and a decrease in the number and size of the trabeculae of cancellous bone (but normal chemical composition), resulting in increased fracture incidence. "After construction the miRNA-gene interaction network, we identified 6 hub miRNAs (hsa-miR-18b-3p, hsa-miR-361-3p, hsa-miR-484, hsa-miR-519e-5p, hsa-miR-940, and hsa-miR-1275) and 6 hub genes (THBS1, IFNAR2, ARHGAP5, TUBB2B, FLNC, and NTF3) for osteoporosis." (PMID 35757478, 2022). "And in our study, for the first time, the intimate association of the other 3 miRNAs (hsa-miR-18b-3p and hsa-miR-519e-5p) and 4 genes (IFNAR2, ARHGAP5, FLNC, and NTF3) with osteoporosis was discovered." (PMID 35757478, 2022).
Salmonella Infections (1 paper, 2024). Infections with bacteria of the genus SALMONELLA.
tumor (31 papers, 2009 to 2025). "miR-486-5p has also been suggested to act as a tumor suppressor by targeting ARHGAP5 and PIK3R1, thereby facilitating NSCLC progression." (PMID 41451087, 2025). "We used the “Similar Genes Detection” module of GEPIA2 to obtain the top 100 ARHGAP5 or ARHGAP11A correlated genes based on the datasets of all TCGA tumor and normal tissues." (PMID 38783033, 2024). "Tumor stage, differentiation degree, and ARHGAP5 expression were significantly correlated with survival." (PMID 38783033, 2024). "The protein expression level of ARHGAP5 was related to tumor size (p = 0.045), lymph node metastasis (p < 0.001) and tumor stage (p < 0.001)." (PMID 38783033, 2024). "The upregulation of hsa_circ_0003258 promotes tumour formation via the hsa_circ_0003258/miR 653p/ARHGAP5 axis, as well as the hsa_circ_0003258/IGF2BP3/HDAC4 axis, according to a recent study." (PMID 36840946, 2023). "The molecular mechanisms of DUSP5P1 as a tumor-promoting factor involved direct induction of the tumor promoting factor ARHGAP5, resulting in the activation of focal adhesion and MAPK signaling pathways." (PMID 36307394, 2022). "Upregulation of hsa_circ_0003258 drives tumor progression through both hsa_circ_0003258/miR-653-5p/ARHGAP5 axis and hsa_circ_0003258/IGF2BP3 /HDAC4 axis." (PMID 34986849, 2022). "For example, a higher ARHGAP5 correlated with lower Th1/Th2 cell ratio, higher Treg cell, and lower M1 macrophage infiltration, indicating a relatively tumor-promoting microenvironment." (PMID 34307347, 2021). "We first declared its anti-tumor effects in BC and found downstream protein ARHGAP5 by combining bioinformatic and RNA-RNA pulldown analysis." (PMID 34285193, 2021). "Higher ARHGAP5 correlates with lower Th1/Th2 cell ratio, higher Treg cell, and lower M1 macrophage infiltration, which indicates a relative tumor-promoting microenvironment." (PMID 34307347, 2021). "Taken together, we found that circUBE2K is a tumor-promoting circRNA in BC that functions as a ceRNA to regulate ARHGAP5 expression via sponging miR-516b-5p." (PMID 34285193, 2021). "RNA-Seq analysis and validation with immunoblotting showed that ARHGAP5 was markedly overexpressed in liver metastatic tissues compared to matched primary tumor tissues." (PMID 32483433, 2020). "In vitro, miR-486-5p down-regulation promotes tumor progression and metastasis by targeting Rho GTPase-activating protein 5 (ARHGAP5)." (PMID 30813457, 2019). "Data from Kaplan–Meier plotter also indicated that lower expression of ARHGAP5 in the tumor results in a longer survival period." (PMID 30250020, 2018). "The data showed that ARHGAP5 expression was positively correlated with tumor size (p = 0.003), depth of tumor infiltration (T stage, p < 0.001), local lymph node metastasis (N stage, p = 0.003), and clinical stage (TNM stage, p < 0.001)." (PMID 30250020, 2018). "Analysis of GC samples in TCGA database showed that overall survival periods are shorter among patients with higher ARHGAP5 levels in the tumor." (PMID 30250020, 2018). "The expression of ARHGAP5 was increased in GC, and positively correlated with tumor size, tumor infiltration, lymph node metastasis, and clinical stage." (PMID 30250020, 2018). "Researches have shown that ARHGAP5 can play an oncogenic role in promoting tumor progression and metastasis." (PMID 25961434, 2015). "Apart from CTNNB1, we’ve identified several cancer-related gene mutations, including PML, HSP90AA1, BAZ1A, ARHGAP5, LHFPL6 in the primary tumor of HB, which may also contribute to the carcinogenesis of HB." (PMID 35860547, 2022). "circUBE2K knockdown significantly reduced the growth rate and weight of BC tumor, which could be rescued via miR-516b-5p inhibition or ARHGAP5 overexpression." (PMID 34285193, 2021). "ARHGAP5 was identified as an oncogene which can promote tumor metastasis and proliferation." (PMID 32429941, 2020).